ARSF (arylsulfatase F)
Description:
Exhibits arylsulfatase activity towards the artificial substrate 4-methylumbelliferyl sulfate.
Synonyms: ASF
Tractability: Antibody: UniProt places it where antibodies can reach, with high confidence; UniProt predicts a signal peptide or a membrane-spanning region; its Gene Ontology location is reachable by antibodies, with medium confidence.
Gene: Protein-coding gene on chromosome X (3,040,235 to 3,112,822, forward strand). Ensembl gene ENSG00000062096.
Subcellular location: Secreted
Subcellular location (Human Protein Atlas): Cytosol; Vesicles; Predicted to be secreted
Pathways (Reactome):
Metabolism: Glycosphingolipid catabolism
Metabolism of proteins: The activation of arylsulfatases
Gene Ontology:
Molecular function: arylsulfatase activity
Cellular component: extracellular exosome; endoplasmic reticulum lumen; extracellular region
Homologues: Orthologues: chimpanzee ARSF (99% identical), macaque ARSF (94% identical), dog ARSF (74% identical), Caenorhabditis elegans sul-2 (24% identical), zebrafish arsib (23% identical), Drosophila melanogaster CG7402 (23% identical), Drosophila melanogaster CG32191 (22% identical), Drosophila melanogaster CG7408 (22% identical), Caenorhabditis elegans sul-3 (21% identical), Drosophila melanogaster Sulf1 (18% identical), zebrafish sulf2a (18% identical), zebrafish gnsb (17% identical), and 3 more. Paralogues in human: ARSD (58% identical), ARSH (56% identical), ARSL (56% identical), STS (48% identical), ARSG (29% identical), GALNS (28% identical), ARSA (28% identical), ARSI (23% identical), ARSB (23% identical), ARSJ (22% identical), SGSH (21% identical), IDS (19% identical), and 4 more.
Diseases named in the same sentence as ARSF in open-access papers:
ARSF is named in the same sentence as 4 diseases in open-access papers, as found by Europe PMC text mining. Sharing a sentence is not in itself a finding about the gene and the disease. The quoted sentences say what the papers report.
psoriasis (1 paper, 2020). An autoimmune condition characterized by red, well-delineated plaques with silvery scales that are usually on the extensor surfaces and scalp. "ARSF belong to the family of sulfatases and has been suggested as a new marker for psoriasis in a mRNA-seq analysis of skin in humans." (PMID 32556497, 2020).
cancer (1 paper, 2020). A tumor composed of atypical neoplastic, often pleomorphic cells that invade other tissues. "However, 2 of the 17-metabolism risk genes, including SPTSSA and ARSF have not been studied in cancers." (PMID 33042807, 2020).
ARSF also shares sentences with these, for which no sentence is quoted: autism (1 paper); mental-retardation (1).